IL6 (interleukin 6)
Diseases named in the same sentence as IL6 in open-access papers (continued):
Sharing a sentence is not in itself a finding about the gene and the disease.
depression (continued). "Another study has shown rapid decreases in levels of IL-6 and TNF-α, as well as a correlation between the decrease in TNF-α and a reduction in the Montgomery–Asberg Depression Rating Scale (MADRS) score." (PMID 34248517, 2021). "An extensive meta-analysis of world reports largely confirms the positive correlation of the levels of some of the inflammatory markers, such as IL-1, IL-6, CRP and TNF-alpha with depression." (PMID 34945157, 2021). "For example, mindfulness-based stress reduction (MBSR), CBT and supportive-expressive dynamic psychotherapy appear to reduce inflammatory markers (e.g., IL-6, TNF-α) in several diseases with comorbid depression." (PMID 33961667, 2021). "Third, observational data indicate that peripheral inflammatory biomarkers, including interleukin-6 (IL-6), and C-reactive protein (CRP), are consistently elevated in depression." (PMID 34589778, 2021). "We examine the relation, interaction, and ratio between the neurotrophic brain-derived neurotrophic factor (BDNF) and the proinflammatory cytokines interleukin-6 (IL-6) and tumor necrosis factor α (TNF-α), and depression severity during ECT." (PMID 34841285, 2021). "In the present study IL-6, TNF-α, BDNF, and depression severity before, during, and after ECT were examined in LLD." (PMID 34841285, 2021). "Ketamine administration decreased the levels of IL-6, TNF-α, and IL-1β and suppressed the activation of NF-κB in depressed mice, suggesting pro-inflammatory inhibition plays an important role in depression treatment." (PMID 34772918, 2021). "Specifically, IL-6 and TNF-α have been identified as the only two cytokines that are consistently elevated in diagnosed major depression." (PMID 34589733, 2021). "Meta-analyses of cross-sectional studies confirm elevated concentrations of circulating inflammatory cytokines and acute phase proteins, like interleukin-6 (IL-6) and C-reactive protein (CRP), in patients with depression as compared to controls." (PMID 34729541, 2021). "Reserpine, which induces anxiety and depression, increased levels of proinflammatory cytokines, TNF-α, IL-6, IL-12, and IFN-γ, mRNA, which induce inflammation and regulate immune cells in serum." (PMID 34220460, 2021). "A meta-analysis based on 29 studies of serum cytokines indicated increased sIL-2R, IL-6, and TNF-α levels, supporting the notion that elevated cytokine proinflammatory levels contribute to the pathophysiology of depression." (PMID 34200240, 2021). "For example, some rodent research reports showed that central and peripheral concentrations of inflammatory factors, especially IL-1 β, IL-6, and TNF-α, increased after the depression model was established by chronic unpredictable mild stress (CUMS)." (PMID 34531719, 2021). "NE acts on microglia and regulates the release of inflammatory factors such as interleukin 6 (IL‐6), interleukin 1β (IL‐1β), and tumor necrosis factor α (TNF‐α); therefore, NE regulates neuroinflammation, neuropathic pain, anxiety, and depression." (PMID 37786561, 2021). "The inflammatory etiology of fatigue and depression in MS was supported by evidence of increased serum and CSF concentration of inflammatory mediators such as TNF, interleukins (IL-1a, IL-1b, IL-6), IFNγ, and neopterin." (PMID 35242093, 2021). "A meta-analysis demonstrated that there was a significant correlation between depression and C-reactive protein (CRP) and IL-6 in children and adolescents." (PMID 34875999, 2021). "Peripheral IL‐6 is necessary for development of maladaptive synaptic plasticity in the NAc of susceptible mice following psychosocial stress (Wang, Hodes, Zhang, Zhang & Zhao, 2018), suggesting that BBB leakiness could actively participate in depression pathogenesis." (PMID 31421056, 2021). "There is a study showing that depression is positively correlated with interleukin- (IL-) 1, C-reactive protein (CRP), and IL-6 in community and clinical samples." (PMID 34712368, 2021).
depression (continued). "It has been shown that the levels of pro-inflammatory cytokines, mainly the interleukins (IL), such as, IL-1, IL-6, IFN-γ, and TNF-α, are elevated in the serum of patients suffering from depression." (PMID 34248517, 2021). "The IL-1β, IL-6, and TNF-α proinflammatory cytokines were previously reported as elevated in patients with depression and appear to play significant roles in the pathogenesis of major depression." (PMID 34209804, 2021). "Il‐6 correlated further with the WHO Quality of Life score (ρ = −0.287, p = .030), as well as with the Geriatric Depression Scale (ρ = 0.297, p = .025)." (PMID 33655551, 2021). "The levels of interleukin-1 beta (IL-1β), interleukin-6 (IL-6), and tumor necrosis factor alpha (TNF-α) in the serum of patients with depression are also significantly higher than those of normal people." (PMID 33790789, 2021). "Increased plasma inflammatory markers including interleukin (IL)-6 and tumor necrosis factor (TNF)-α have been found in people with anxiety and depression particularly in those who fail to respond to classical treatments." (PMID 33807290, 2021). "Meta-analyses reported strong evidence of significantly increased levels of c-reactive protein (CRP), IL-1, IL-6, TNF-α and soluble IL-2 receptor in the serum of major depressive disorder (MDD) patients." (PMID 34440101, 2021). "A relevant meta-analysis showed that the concentrations of inflammatory factors such as IL-6 and TNF were higher than normal in patients with depression." (PMID 34257681, 2021). "Chang-Yu-Xiao-Yao-San can reduce the expression of inflammatory factors IL-6, IL-8, and TNF-α in the serum of patients with chronic hepatitis B combined with depression, and relieve the symptoms of depression in patients." (PMID 33790789, 2021). "Depression has an inflammatory component with elevated levels of proinflammatory cytokines, such as tumor necrosis factor-alpha (TNF-α), interleukin (IL)-6, IL-1, and C-reactive protein." (PMID 34948222, 2021). "For IL-6, per-unit increase in higher genetically-predicted IL-6 activity was associated with increased risk for depressive symptoms (1-sample MR: OR=1·32, 95% CI 1·03–1·67; 2-sample MR: OR=1·34, 95% CI 1·05–1·72), but not with probable depression or either anxiety outcome." (PMID 34505025, 2021). "Recent studies both pre-clinical and clinical have advocated for the functional role of IL-6 in development of MDD and suggested a great potential for targeting this cytokine to open new avenues in pharmacotherapy of depression." (PMID 33593388, 2021). "Since inflammation has been proposed to be a causative mechanism in the development of chronic stress-induced depression, we assessed the inflammatory cytokines TNF-α and IL-6." (PMID 34614119, 2021). "Elevated levels of various inflammatory biomarkers, such as IL-6 and TNF-α, and increased high-sensitivity C-reactive protein (CRP) concentrations were found to be present in patients with mild to moderate depression six months following stroke." (PMID 34471414, 2021). "Lastly, the group with type 2 diabetes also used less alcohol, were less physically active, had a higher prevalence of depression, a history of CVD and cognitive impairment and higher plasma concentrations of IL-6 and TNF-α compared with those with NGM." (PMID 34409496, 2021). "The colon levels of IL-6, IL-1β, and TNF-α in the depression model group was significantly increased (p < 0.01; F = 19.265, F = 38.3, and F = 57.968, respectively) compared with the control group." (PMID 33505499, 2021). "All those findings share, that increased inflammation in the hippocampus induces anxiety and depression-like behavior in rodents, and those behavioral symptoms could be attenuated through anti-inflammatory agents which reduced among other pro-inflammatory cytokines IL-6." (PMID 33683478, 2021).
depression (continued). "Miller et, al., found that among healthy adults without any acute infectious disease or chronic medical illnesses, those who met clinical depression criteria had significantly higher levels of both CRP and IL-6." (PMID 32691611, 2021). "In a recent study, IL-6 and QUIN plasma levels were positively correlated in women with peripartum onset depression (PPD)." (PMID 34072767, 2021). "The KBD formula normalized UMCS-induced anhedonia and hopeless behaviors in mice by restoring expression of the depression-related genes BDNF, CREB, GR, SGK1, FKBP5, IL-1β, IL-6, and TNF-α in the frontal cortex and hippocampus brain regions." (PMID 34358084, 2021). "Increasing levels of proinflammatory mediators such as IL-1, IL-2, IL-6, and TNF-α have been observed in patients with depression." (PMID 33513891, 2021). "More recent reviews resume that IL-1 ß, IL-6, TNF-α, and C-reactive protein (CRP) are the most consistently identified biomarkers of inflammation in depression." (PMID 34204400, 2021). "A high level of interleukin-6 (IL-6) was predominantly observed in mania, tumor necrosis factor-α (TNF-α) was elevated in both depression and mania and C-reactive protein (CRP) level was even increased in euthymia." (PMID 34381386, 2021). "Animal experimental results also show that Chang-Yu-Xiao-Yao-San inhibits an over-expression of serum IL-6, IL-8, and TNF-α in LPS-induced depression model rats and increased the content of hippocampal 5-HT in rats." (PMID 33790789, 2021). "Recent evidence from both clinical and preclinical research studies indicates that elevations in pro-inflammatory cytokines, including IL-6, TNF-α, and NO, act as a common mechanism for the impact relationship of depression and fatigue in patients with CRF." (PMID 34122094, 2021). "The ‘coded’ effect associated with proinflammation activates and maintains a cascade of biological (IL-6, IL-17, TNF, TRYCATs) and psychological (anxiety) events acting on a feedback principle and contributing to drug resistance in depression." (PMID 33385173, 2021). "Several studies have further found that the hippocampal concentrations of the pro-inflammatory cytokines IL-6, IL-1β, and TNF-α are elevated in mice with depression-like behavior." (PMID 34220460, 2021). "PPI network analysis showed that VEGFA, EGFR, CASP3, IL6, ESR1, and other targets have important implications in the treatment of depression with XPJYD." (PMID 34257681, 2021). "A cohort study followed up for 6 years discovered that higher baseline levels of plasma IL-6 predicted chronic recurrent course in women with MDD, and cytokines were expected to be biomarkers for predicting recurrence of depression." (PMID 34079622, 2021). "The pro-inflammatory cytokines such as interleukin-6 (IL-6), interleukin-1β (IL-1β), and tumor necrosis factor-α (TNF-α) in peripheral and central nervous system are significantly increased in patients with depression." (PMID 34772918, 2021). "Another study reported that there was a positive correlation between depression severity in patients with CFS and IL-6 levels." (PMID 33868142, 2021). "In patients with depression, the levels of CRP, IL-6, IL-12, and TNF-α are significantly elevated, indicating a pro-inflammatory state." (PMID 35087377, 2021). "IL-6 and TNF-α have been reported to be elevated in mice showing behavioral despair and in patients with depression." (PMID 34040528, 2021). "IL-6, TNF-α and IFN-γ in the periphery are moderately related to self-reported depression symptoms during MS relapse, and TNF-α levels during this time are strongly linked to long-term depression at follow up, 3–6 months later." (PMID 34589733, 2021). "Luteoklin, quercetin, kaempferol and other active compounds in Epicedium can regulate multiple signaling pathways and targets such as IL6, AKT1, and EGF, therefore playing therapeutic roles in depression." (PMID 34479552, 2021).
depression (continued). "CRP, sTNFR1, IL-6 and its soluble receptor and monocyte chemoattractant protein-1 (MCP-1) were found to be higher in BD in comparison with unipolar depression." (PMID 33946871, 2021). "Second, clinical evidence has indicated that VNS is associated with marked peripheral increases in pro- and anti-inflammatory circulating cytokines, such as IL-6, TNF-α, and TGF-β in patients with resistant depression." (PMID 34526917, 2021). "Reduce the expression of cytokines IL-1β, IL-6, TNF-α, and improve depression-like behavior in CUMS rats." (PMID 35185541, 2021). "High levels of PTSD and depression symptoms may lead to chronic dysregulation of the hypothalamic–pituitary–adrenal axis and increased levels of systemic inflammatory markers, including interleukin-6 and C-reactive protein, which may be elevated prior to RA onset." (PMID 34071429, 2021). "Si-Ni-San reduces the release of inflammatory factors IL-1β, IL-6, IL-2, and TNF-α in the peripheral fluid of patients with post-stroke depression and regulates the over-activation of the HPA axis, thereby exerting an antidepressant effect." (PMID 33790789, 2021). "Serum interleukin‐6 (IL‐6), irisin, brain‐derived neurotrophic factor (BDNF), kynurenine, and cathepsin B were analyzed and compared to surrogates of depression and quality of life." (PMID 33655551, 2021). "A variety of proinflammatory cytokines such as IL-1β, IL-6, TNF, and Toll-like receptor 3 (TLR3) has been found to overexpress depression." (PMID 34650925, 2021). "Demonstrated in some studies is the long-lasting increased level of such cytokines as, for example, IL-6, IL-1β and TNF-α, which means a longer exposure to factors contributing to the development of depression." (PMID 34575258, 2021). "Relatively consistent findings showed an increase in several cytokines, including interleukin-6 (IL-6), interleukin-1 (IL-1), tumor necrosis factor-alpha (TNF-α), and C-reactive protein (CRP) in patients with depressive disorder versus healthy controls (HCs)." (PMID 34576215, 2021). "A significant positive correlation between Montgomery–Åsberg Depression Rating Scale (MADRS) scores and CSF IL-6 levels were reported." (PMID 32244611, 2020). "Inflammatory cytokines, IL-6, TNF-α and IFN-γ are consistently upregulated in individuals with depression and many antidepressant medications have anti-inflammatory effects." (PMID 32539844, 2020). "Proinflammatory cytokines, including IL-1β, IL-6, and TNF-α, are elevated in experimental and clinical studies of depression." (PMID 32410849, 2020). "Interleukin-6 (IL-6) and tumor necrosis factor-α (TNF-α) levels were significantly increased in patients with depression." (PMID 33447180, 2020). "IL-6 and STAT3 have been previously shown to be involved in serotonin transporter function and depression-like behavior." (PMID 32998701, 2020). "The main general markers of the cooccurrence of chronic pain and depression were related to central inflammation, particularly, tumor necrosis factor (TNF)-α, interleukin (IL)-1β, and IL-6, as well as peripheral discrepancies in cortisol levels." (PMID 32849076, 2020). "In this sense, the main general markers of the cooccurrence of chronic pain and depression are related to central inflammation, particularly TNF-α, IL-1β, and IL-6." (PMID 32849076, 2020). "Emerging evidence indicates that proinflammatory cytokines, including interleukin (IL)-1, IL-6, and tumor necrosis factor-alpha (TNF-α), contribute to the pathophysiology of depression." (PMID 33029297, 2020). "STAT3 is one of the transcription factors regulating the production of the cytokine IL-6, IL-10, TNF-α, and IL-1β, which have been shown to be involved in depression." (PMID 32655424, 2020). "PD patients have elevated levels of CRP, CCL-2, IL-6, and of TNF-alpha, correlating partially with fatigue, depression and anxiety, and with cognitive deficits." (PMID 32072462, 2020).
depression (continued). "A meta-analysis of 24 studies reported that interleukin-6 (IL-6) and tumor necrosis factor-α (TNF-α) were found in higher concentrations in individuals with depression, compared with control participants." (PMID 33424964, 2020). "We found increases in the mean levels of CRP, IL-3, IL-6, IL-12, IL-18, sIL-2R and TNF α in patients with depression." (PMID 32113908, 2020). "A dysregulation in the levels of inflammatory proteins such as IL-12, TNF, IL-6 and IFN-γ have been found to be significantly correlated with depression." (PMID 32998701, 2020). "Postmortem analysis of the PFC of suicide victims has shown elevated levels of inflammatory cytokines such as IL‐1β, IL‐6, and TNF‐α 40, and suicide victims that have suffered from depression and schizophrenia exhibit increased microglial reactivity." (PMID 32125791, 2020). "However, the roles of CUMS exposure, a common model to induce depression in rodents leading to glucose metabolic disorder, and of cytokine IL-6-mediated disruption of glucose homeostasis signaling in hypothalamus in the pathogenesis of depression comorbid with glucose intolerance, remain unknown." (PMID 32655424, 2020). "Our meta-analysis finds evidence that mean-scaled variability, measured as CVR, is reduced in patients with depression for CRP, IL-12 and sIL-2R, while it is unchanged for IL-3, IL-6, IL-18 and TNF α." (PMID 32113908, 2020). "Peripheral levels of pro-inflammatory cytokines IL-6 and TNF-α are elevated in depression patients who were SSRI resistant compared to patients with depression, but in remission whose cytokine levels were similar to matched healthy controls." (PMID 32539844, 2020). "Compared with these two groups, higher levels of SOD, CAT, and GSH-Px but lower levels of CRP, IL-6 and TNF-α were observed in the depression group." (PMID 32973539, 2020). "IL-1, IL-6, IL-1β, TNF-α, and CRP are considered markers of the initiation, relapse, and progression of depression." (PMID 32922295, 2020). "Among inflammatory markers, IL-6, C-reactive protein (CRP), TNF-α and soluble interleukin-2 receptor (sIL-2R) appear to have the greatest potential to serve as markers for depression." (PMID 33255237, 2020). "Clinical studies also show that pro-inflammatory cytokines, e.g. TNF-α, IL-1β, IL-6, CCL-2, and IL-18, increase in patients with depression or anxiety." (PMID 32010477, 2020). "A meta-analysis of 82 studies provided evidence that peripheral levels of several pro-inflammatory cytokines (i.e. interleukin-6 and TNF-α) were more elevated in patients with major depression disorder compared to healthy controls." (PMID 32072134, 2020). "Several studies have shown increased levels of TNF-α, IL-6, and C-reactive protein (CRP) in patients with depression." (PMID 33343332, 2020). "Previous studies found that pro-inflammatory cytokines, including tumor necrosis factor-α (TNF-α) and interleukin (IL)-6, IL-1β, and C-reactive protein (CRP), are markedly increased in the blood and CSF of patients with depression." (PMID 32922295, 2020). "However, whether depression susceptibility to hyperglycemia is associated with IL-6-mediated disruption of glucose homeostasis, is not clear." (PMID 32655424, 2020). "Previous studies also have demonstrated that the serum levels of IL-6, interleukin-1β, TNF-α, and other pro-inflammatory cytokines were increased in depression patient under long-term chronic stress." (PMID 32655450, 2020). "We also found that positive changes in TNF-α, IL-6, IL-10 and CRP levels significantly correlated with higher reduction in depression symptoms." (PMID 31375659, 2019). "Therefore, if CRP and IL-6 cannot be simply considered biomarkers of inflammation, then the association of CRP and IL-6 with the development of depressive symptoms cannot be interpreted to provide evidence for a link between inflammation and depression that is not due to a medical condition." (PMID 30769887, 2019).